CD47 (CD47 molecule)
Diseases named in the same sentence as CD47 in open-access papers (continued):
Sharing a sentence is not in itself a finding about the gene and the disease.
acute monocytic leukemia (1 paper, 2023). Acute monoblastic leukemia (AML-M5), is one of the most common subtypes of acute myeloid leukemia (AML) that is either comprised of more than 80% of monoblasts (AML-M5a) or 30-80% monoblasts with (pro)monocytic differentiation (AML-M5b). "Differently, macrophage phagocytosis of acute monocytic leukemia (M4) is known to be dependent on CD47 activation and the chemotactic responsiveness effects of M4 and M5b, but not M5a leukemic cells are comparable to that of normal monocytes." (PMID 37549179, 2023). "In acute monocytic leukemia, the phagocytic ability of macrophages is sensitive to CD47." (PMID 37549179, 2023).
adenovirus infection (1 paper, 2019). "Conversely, the over-expression of MIAT by adenovirus infection efficiently increased ox-LDL-induced CD47 expression." (PMID 30755588, 2019).
amyotrophic lateral sclerosis (1 paper, 2021). Amyotrophic lateral sclerosis (ALS) is a neurodegenerative disease characterized by progressive muscular paralysis reflecting degeneration of motor neurons in the primary motor cortex, corticospinal tracts, brainstem and spinal cord. "It would similarly be interesting to see if CD47 expression could aid other cell types that undergo degeneration, such as retinal ganglion cells in glaucoma or motor neurons in amyotrophic lateral sclerosis." (PMID 34197341, 2021).
ANCA-associated vasculitis (1 paper, 2024). "NETs associated with vasculitis are thought to escape efferocytosis due to the expression of CD47 and CD47 blockade has been shown to mitigate ANCA-associated vasculitis." (PMID 39039207, 2024).
Atrophy (1 paper, 2021). Any weakening or degeneration, especially through lack of use. "Deletion of Thbs1 effectors/receptors, including ATF6α, CD36 or CD47 does not diminish Thbs1-dependent cardiac atrophy." (PMID 34168130, 2021). "Taken together, these results indicate that Thbs1-mediated cardiac atrophy and premature lethality are independent of CD36 or CD47." (PMID 34168130, 2021).
bacteremia (1 paper, 2020). "The CD47 knockout mice displayed a reduced pulmonary lung edema, reduced bacteremia, increased neutrophil infiltration, therefore, suggesting that CD47 could be a potential target for the treatment of acute lung injury." (PMID 32882841, 2020).
bladder squamous cell carcinoma (1 paper, 2023). A squamous cell carcinoma of the bladder arising from metaplastic epithelium. "Ex vivo molecular imaging of 25 BC samples (including two patients with bladder squamous cell carcinoma) illustrated that fluorescent tracer dependent on anti-CD47 targeting guidance attached to CD47 molecules on the surface of tumor cells." (PMID 36937442, 2023).
bone metastasis (1 paper, 2018). Transfer of a neoplasm from its primary site to bones. "The same patient had a primary tumor negative for CD47 but developed a bone metastasis with a high expression of CD47 after seven years; this suggests that CD47 expression was probably acquired during the initiation of metastatic dissemination." (PMID 30200242, 2018).
bone sarcoma (1 paper, 2021). A sarcoma that arises from the bone. "Many pediatric tumors, including bone sarcomas and synovial sarcomas, demonstrate surface expression of SIRPα on a par with that of CD47, suggesting that the interaction between the two is likely relevant." (PMID 33717062, 2021).
carcinoid (1 paper, 2021). "CD47 expression was apparent in 25% of carcinoid, 25% of atypical, 40% of large cell, and 24% of small-cell tumors." (PMID 34195295, 2021).
Cerebral ischemia (1 paper, 2023). Restriction of arterial blood supply to the brain associated with insufficient oxygenation to support the metabolic requirements of the tissue. "These research opens new horizons in the potential therapeutic applications of targeting CD47 to attenuate neuronal damage in cerebral ischemia." (PMID 38125492, 2023).
Cholecystitis (1 paper, 2022). The presence of inflammatory changes in the gallbladder. "In addition, 4-methylumbelliferone (4MU), a cholecystitis drug, can disrupt the CD47/SIRPα axis by disturbing glioblastoma HA synthesis." (PMID 35410993, 2022).
Chronic colitis (1 paper, 2019). A chronic inflammatory disease of the large intestine (colon, cecum and rectum). "Herein, our findings indicate that loss of CD47 on IEC rendered mice more susceptible to DSS-induced chronic colitis." (PMID 31676794, 2019). "The same study also reported that Cd47-null mice are protected against prolonged administration of DSS to model chronic colitis owing to attenuated granulopoiesis leading to reduced PMN accumulation in colonic mucosa." (PMID 31676794, 2019).
classic Hodgkin lymphoma (1 paper, 2026). Classical Hodgkin lymphoma (CHL) is a B-cell lymphoma characterized histologically by the presence of large mononuclear Hodgkin cells and multinucleated Reed-Sternberg (HRS) cells. "However, the critical role of CD47 in classic Hodgkin lymphoma (CHL) and its association with immune checkpoints and tumor microenvironment (TME) remain unclear." (PMID 41811881, 2026).
co-infection (1 paper, 2024). "To investigate the necessity of airway epithelial CD47 in the context of viral-bacterial co-infection, we established two in vivo mouse models of super-infection." (PMID 38693120, 2024).
coagulopathies (1 paper, 2022). "Further genetic modifications included transgenic overexpression of human proteins to decrease cellular injury (CD47 and Hemoxygenase 1), complement activation (hCD55 and hCD46) and coagulopathies (human Endothelial Cell Protein C Receptor and human Thrombomodulin)." (PMID 36568986, 2022).
cognitive decline (1 paper, 2024). "The observations presented here show that both C1q and CD47 are dysregulated during normal aging in the primate brain in association with myelin breakdown in white matter and cognitive decline." (PMID 39399501, 2024).
coronary atherosclerosis (1 paper, 2021). Atherosclerosis of the coronary vasculature. "Further, continuous upregulation of CD47 has been reported in necrotic cells in carotid and coronary atherosclerosis in both humans and animal models." (PMID 34349643, 2021).
craniopharyngioma (1 paper, 2024). A benign, partly cystic, epithelial tumor of the sellar region, presumably derived from Rathke pouch epithelium. "Similarly, CD47 promotes MAPK/ERK activation in adamantinomatous craniopharyngioma cells to support epithelial-to-mesenchymal transition (EMT)-induced cell migration." (PMID 39039207, 2024).
dermatitis (1 paper, 2025). An inflammatory process affecting the skin. "Transcriptomic analysis and machine-learning models enable patient stratification, allowing for the identification of biomarkers such as ADAM8, CD47, BATF, SELE, IL-37 that may aid in diagnosis and differentiating ACD from other forms of dermatitis." (PMID 40181807, 2025).
dermatomyositis (1 paper, 2014). Dermatomyositis (DM) is a type of idiopathic inflammatory myopathy characterized by evocative skin lesions and symmetrical proximal muscle weakness. "TSP-1, CD36, and CD47 expression have been reported to be upregulated in inclusion body myositis and dermatomyositis muscle specimens." (PMID 25501558, 2014).
dilated cardiomyopathy (1 paper, 2017). Cardiomyopathy which is characterized by dilation and contractile dysfunction of the left and right ventricles. "It has been shown that CD47 is expressed in abundance on apoptotic neonatal cardiocytes, and mice lacking thrombospondin-2, a CD47 ligand, exhibit impaired cardiomyocyte survival and dilated cardiomyopathy leading to higher mortality." (PMID 29163503, 2017).
disseminated candidiasis (1 paper, 2015). Systemic candidiasis occurs when Candida yeast enters the bloodstream and may spread (becoming disseminated candidiasis) to other organs, including the central nervous system, kidneys, liver, bones, muscles, joints, spleen, or eyes. "Collectively, these data demonstrate that cd47-/- mice are more susceptible to disseminated candidiasis." (PMID 26010544, 2015). "Because antibodies that block CD47 are entering clinical trials for treating cancer patients, it is important to know whether this treatment could increase their susceptibility to disseminated candidiasis." (PMID 26010544, 2015). "The present study suggests that CD47 plays a protective role against disseminated candidiasis through regulation of T helper cell differentiation and expression of cytokines that modulate this differentiation." (PMID 26010544, 2015). "We show that, in contrast to its ligand TSP1, CD47 supports protective immunity against disseminated candidiasis in a mouse model by limiting host pro-inflammatory cytokine/chemokine expression and by limiting neutrophil infiltration." (PMID 26010544, 2015).
endotoxemia (1 paper, 2016). "Therefore, thrombospondin-1 and its receptor CD47 may be useful targets for limiting the pro-inflammatory effects of lipopolysaccharide and for treating endotoxemia." (PMID 26813769, 2016).
epithelial ovarian tumor (1 paper, 2024). "CD47 is indeed reported to foster epithelial ovarian tumor cell growth, to promote OC progression and metastasis, and to facilitate immune evasion by impeding macrophage phagocytosis." (PMID 39138571, 2024).
erythroleukemia (1 paper, 2025). Acute erythroid leukemia characterised by the presence of at least 50% erythroid precursors and at least 20% myeloblasts in the bone marrow. "Moreover, treated with triptolide resulted in a significant reduction in the protein expression of CD47 and CD126 in the THP-1 macrophage cell line and the KG-1 erythroleukemia cell line, with the fold changes for CD47 were 0.3 (THP-1) and 0.55 (KG-1) in vitro." (PMID 40490812, 2025).
Gaucher disease (1 paper, 2013). Gaucher disease (GD) is a lysosomal storage disorder encompassing three main forms (types 1, 2 and 3), a fetal form and a variant with cardiac involvement (Gaucher disease - ophthalmoplegia - cardiovascular calcification or Gaucher-like disease). "Erythrocytes from patients with untreated Gaucher's disease have been found to have reduced levels of CD47, which can be reversed upon enzyme-replacement therapy." (PMID 23401787, 2013).
glomerulonephritis (1 paper, 2023). A renal disorder characterized by damage in the glomeruli. "Thus, CD47 blockade would protect against developing glomerulonephritis in AAV via restored efferocytosis of ANCA-induced NETs." (PMID 37368493, 2023).
haemolytic anaemia (1 paper, 2021). "However, as a critical regulator of RBCs, CD47 is functionally involved in the maintenance and clearance of RBCs, suggesting that haemolytic anaemia may occur subsequent to the use of an antagonist targeted towards CD47." (PMID 33449453, 2021).
hemophagocytic lymphohistiocytosis (1 paper, 2022). "Since CD47 mAbs activate the phagocytosis of macrophages, CD47 mAb therapy should be avoided in patients with hematological malignancy-associated hemophagocytic lymphohistiocytosis and monocyte/macrophage-related malignancies." (PMID 35978372, 2022).
Hemophagocytosis (1 paper, 2023). Phagocytosis by macrophages of erythrocytes, leukocytes, platelets, and their precursors in bone marrow and other tissues. "However, there are some reports that the removal of an inhibitory signal by a CD47–SIRPα interaction is not sufficient for prominent hemophagocytosis and that the additional activation of macrophages is needed to induce hemophagocytosis." (PMID 37111479, 2023).
hemorrhagic stroke (1 paper, 2017). A stroke caused by a bleed on the brain. "TSP-1 participates in angiogenesis, the inflammatory response, apoptosis, and fibrosis after hemorrhagic stroke through binding to various molecules including but not limited to CD36, CD47, and TGF-β." (PMID 29214179, 2017).
hereditary anemia (1 paper, 2011). "Moreover, in hemolytic cases, the membrane levels of sCLU were positively correlated with those of CD47 protein that is reduced in cases of hereditary anemias and during in vitro aging of human RBCs." (PMID 21998749, 2011).
Hydrocephalus (1 paper, 2025). Hydrocephalus is an active distension of the ventricular system of the brain resulting from inadequate passage of CSF from its point of production within the cerebral ventricles to its point of absorption into the systemic circulation. "Reducing the secretion of pro-inflammatory cytokines, depleting macrophages, microglia, and neutrophils, or inhibiting their activation, provides a therapeutic option for hydrocephalus, e.g., CD47-blocking antibodies, mesenchymal stem cell transplantation, and minocycline." (PMID 39908266, 2025).
Hypercalcemia (1 paper, 2024). An abnormally increased calcium concentration in the blood. "This research has emphasized that suppressing CD36 or CD47 mitigates osteoclast formation, thereby inhibiting PTH-induced hypercalcemia in mouse models." (PMID 38167957, 2024).
Hypercholesterolemia (1 paper, 2019). An increased concentration of cholesterol in the blood. "In a separate cohort of Cd47−/−mice, we determined that the effects observed were not contingent on hypercholesterolemia because chow fed mice displayed a similar DC and T cell phenotype." (PMID 31337788, 2019).
Insulinoma (1 paper, 2013). "Utilizing an in vivo model in the present study, we investigated whether genetically engineered expression of mouse CD47 in rat insulinoma cells (INS-1E) could inhibit macrophage-mediated xenograft rejection." (PMID 23472187, 2013). "Thus, the in vivo transplant model proved that genetically engineered expression of mouse CD47 in rat insulinoma cells could inhibit macrophage-mediated xenograft rejection." (PMID 23472187, 2013). "To determine whether expression of mouse CD47 on rat cells could efficiently prevent their phagocytosis by mouse macrophages, we generated rat insulinoma cell lines that express mouse CD47 by transfecting rat cells with a mouse CD47-expressing plasmid, pRc/CMV-mouse CD47." (PMID 23472187, 2013).
invasive carcinoma (1 paper, 2024). A carcinoma that is not confined to the epithelium, and has spread to the surrounding stroma. "There are studies in the literature that evaluate CD47 expression not only in solid tumors but also in precancerous lesions and invasive carcinomas." (PMID 39795582, 2024). "The progressively increasing CD47 expression across the AK-ISCC-SCC spectrum suggests that CD47 expression may play a role in the progression from in situ malignancy to overt invasive carcinoma." (PMID 39795582, 2024).
Kawasaki disease (1 paper, 2018). A rare inflammatory disease characterized by an acute febrile, systemic, self-limiting, medium-vessel vasculitis primarily affecting children. "Decreased glycophorin A and CD47 expression, as well as the externalization of phosphatidylserine, were measured in RBCs from patients with Kawasaki disease during the early phase of the disease." (PMID 29948255, 2018).
laryngeal squamous cell carcinoma (1 paper, 2022). A squamous cell carcinoma that arises from the larynx. "B6H12.2 is a commercially available anti-CD47 monoclonal antibody that efficiently blocks the interaction between CD47 and SIRPα in Laryngeal Squamous Cell Carcinoma (LSCC) in vitro." (PMID 36293358, 2022).
liver disease (1 paper, 2025). "CD47 gene knockout and anti-CD47 antibody treatment exhibit distinct effects in liver disease models, likely due to differences in mechanisms of action and duration of intervention." (PMID 40630093, 2025).
lympho-proliferative disorders (1 paper, 2012). "Yet, CD47−/− mice do not display lympho-proliferative disorders as seen in Fas-deficient mice." (PMID 22870271, 2012).
malignant mesothelioma (1 paper, 2021). A malignant neoplasm of the pleura or peritoneum, arising from mesothelial cells. "The use of BoxA, or a small molecule mimicking its action on CXCR4, may hold promise for malignant mesothelioma, for which there are very few available therapeutic interventions, and more generally for the wide variety of tumors vulnerable to CD47 blockade." (PMID 33956406, 2021).
memory impairment (1 paper, 2023). "Similarly, disruption of the integrin-associated protein (IAP, also known as CD47), causes memory impairment in mice due to its relationship with one of the genes related to memory formation." (PMID 36671492, 2023).
metastatic colorectal cancer (1 paper, 2025). "Because IR700@Nb289‐OMVs plus NIR irradiation combined with CD47 blockade showed better antitumour outcomes, we further extended this combination therapy to metastatic colorectal cancer models." (PMID 40240911, 2025).
metastatic prostate carcinoma (1 paper, 2023). A carcinoma that arises from the prostate gland and has spread to other anatomic sites. "The PRAD-GSE141445 dataset containing metastatic prostate cancer showed high expression of CD47 in CD8+T cells while low expression in B cells." (PMID 37719086, 2023).
monoclonal gammopathy of undetermined significance (1 paper, 2020). "We analyzed CD47 mRNA expression for patients of three stages: healthy (n = 22), monoclonal gammopathy of undetermined significance (MGUS; a premalignant stage of MM) (n = 44), and newly diagnosed MM (n = 559)." (PMID 32012878, 2020).
myxofibrosarcoma (1 paper, 2024). A malignant fibroblastic neoplasm arising from the soft tissue. "Myxofibrosarcomas (MFS) were highly positive for CD47, particularly in the G3 group." (PMID 38493445, 2024).
myxoma (1 paper, 2023). A benign soft tissue neoplasm characterized by the presence of spindle and stellate cells, lobulated growth pattern, and myxoid stroma formation. "This study explores using engineered Myxoma virues (MyxV) encoding CD47 and IFN-γ to fight tumors and boost immune responses in the tumor environment." (PMID 37835397, 2023).
nasopharyngitis (1 paper, 2020). An inflammatory process that affects the nasopharynx. "CD47 expression was higher in NPC samples than in nasopharyngitis tissues." (PMID 32149101, 2020).
necrotizing vasculitis (1 paper, 2023). A type of vasculitis that is comprised of vasculitides that present with necrosis. "Hence, we hypothesized that pathogenic NETs in AAV escape from efferocytosis via the CD47 signaling pathway, resulting in the development of necrotizing vasculitis." (PMID 37368493, 2023).
non-melanoma skin carcinoma (1 paper, 2022). "CD47 expression was associated with tumorigenesis and tumor progression in non-melanoma skin cancers." (PMID 36010209, 2022).
oncocytomas (1 paper, 2024). "When comparing CD47 expression in relation to the pathological tumor stage, in the oncocytoma group, 24 cases were in the T1 stage, and 2 cases were in the T2 stage." (PMID 39795582, 2024). "In our study, when comparing the relationship between CD47 expression and pathological tumor stage, 24 cases in the oncocytoma group were classified as T1, and 2 cases as T2." (PMID 39795582, 2024). "In our study, CD47 expression was detected in the oncocytoma cases, although not at a very high rate." (PMID 39795582, 2024).
osteoarthritis (1 paper, 2021). A noninflammatory degenerative joint disease occurring chiefly in older persons, characterized by degeneration of the articular cartilage, hypertrophy of bone at the margins and changes in the synovial membrane. "The relevance of CD47-integrin association has also been shown in an osteoarthritis murine model and patients with osteoarthritis." (PMID 34944878, 2021). "In both mice and humans with osteoarthritis, there is overexpression of CD47 and αvβ3 integrin, induced by the products of damaged chondrocytes." (PMID 34944878, 2021).